SPP1 (secreted phosphoprotein 1)
Diseases named in the same sentence as SPP1 in open-access papers (continued):
Sharing a sentence is not in itself a finding about the gene and the disease.
liver fibrosis (continued). "The relevance of SPP1 expression with liver fibrosis was further examined in humans and mice." (PMID 38557493, 2024). "Furthermore, soluble egg antigen (SEA) stimulates macrophages to secrete SPP1, which stimulates hepatic stellate cell activation and collagen deposition and promotes the development of liver fibrosis." (PMID 39590301, 2024). "In addition, in these patients, levels of SOX9-regulated proteins such as SPP1, another liver progenitor marker, were increased in the serum and correlated with the severity of liver fibrosis." (PMID 37296834, 2023). "SPP1 expression has been shown to be regulated by promoter methylation in liver fibrosis." (PMID 31555647, 2019). "Our results indicate that an epigenetic alteration, DNA hypomethylation of the Spp1 enhancer, may precede the up-regulation of Spp1 expression and induce the onset of CCl4-induced early-stage liver fibrosis." (PMID 22281153, 2012). "Thus, hepatocyte CEBPA restricted CCl4-induced hepatic fibrosis through reducing Spp1 expression." (PMID 38557493, 2024). "Consequently, targeting SPP1 and decreasing its expression level could represent an effective therapeutic strategy for patients with liver fibrosis and HCC." (PMID 39635536, 2024). "Whether hypermethylation of SPP1 gene can treat liver fibrosis needs to be further investigated." (PMID 37056286, 2023). "As a multifunctional protein, SPP1 is involved in multiple liver diseases by promoting inflammatory responses, cell activation, proliferation, and migration, and is closely related to the occurrence, development, and prognosis of fatty liver, liver fibrosis, and liver cancer." (PMID 35514751, 2022). "As SPP1 is involved in fibrosis regulation and triggers the release of multiple inflammatory cytokines, its activity is increased in NAFLD and paralleled with fibrosis stages, and SPP1 neutralization might be useful for preventing progressive hepatic fibrosis in NASH patients." (PMID 36329886, 2022). "Consequently, modulation of SPP1 by HCV may be critical for liver fibrosis development and represents a potential target for therapy of HCV infection and/or disease progression." (PMID 18590516, 2008). "Conversely, LAMs with low CX3CR1/CCR2 expression and high Trem2, CD63, Gpnmb, and secreted phosphoprotein 1 (Spp1) expression preferentially accumulate in HSC-activated regions, promoting the progression of liver fibrosis." (PMID 41394841, 2025). "Our findings indicate that XCF can significantly reduce the mRNA and protein expression levels of LGALS3 and SPP1 in liver tissue induced by a HFD, thereby alleviating the degree of liver fibrosis in MAFLD mice." (PMID 40124784, 2025). "SPP1, GNMT, CLDN11, and THBS2 were determined in the transformation process of MASH to liver fibrosis." (PMID 38726780, 2025). "Specifically, 680 proteins in cluster 1, including pro- and anti-inflammatory cytokines (e.g., IL-6 and IL-10) and liver fibrosis markers (e.g., ACTA2, KRT19, and SPP1), increased progressively with fibrosis stages." (PMID 39889710, 2025). "Four genes (SPP1, GNMT, CLDN11, and THBS2) were the intersection genes with the potential to affect the transformation process of MASH to liver fibrosis." (PMID 38726780, 2025). "In this study, we utilized four public GEO datasets to obtain four genes (SPP1, GNMT, CLDN11, and THBS2) affecting the transformation of MASH to hepatic fibrosis." (PMID 38726780, 2025). "Osteopontin (OPN), or SPP1, is a multifunctional glycoprotein that plays a critical role in the pathogenesis of liver fibrosis." (PMID 39654627, 2024). "After CCl4 dosing for 4 weeks and 8 weeks, CebpaΔHep mice had higher hepatic Spp1 mRNA, serum OPN, liver fibrosis, and hepatic CD45 staining." (PMID 38557493, 2024). "AAV8-TBG-Cebpa increased hepatic Cebpa mRNA and CEBPA protein, while decreased hepatic Spp1 mRNA, serum OPN, hepatic lipid accumulation, and liver fibrosis, accompanied by a reduction in liver TG, serum ALT, and NEFA without changing other parameters." (PMID 38557493, 2024).
liver fibrosis (continued). "Several reports suggest that osteopontin (OPN) (also known as secreted phosphoprotein 1, SPP1) is induced in human subjects or mice with NASH33,34, and that OPN aggravates hepatic fibrosis in MCD diet-induced NASH mouse model." (PMID 29717162, 2018). "Both curcumin prevention and treatment reduced molecular markers of hepatic fibrosis (Col1a1 mRNA) and inflammation (TNF‐α, SPP1 mRNA)." (PMID 30009570, 2018). "SPP1, a profibrotic factor, plays a crucial role in NASH and liver fibrosis processes." (PMID 40124784, 2025). "Our research investigated the differences in expression and distribution of SPP1 between liver fibrosis and HCC, and discovered that SPP1 was significantly overexpressed in cholangiocytes in cases of liver fibrosis, but it was highly expressed in macrophages in cases of HCC." (PMID 39635536, 2024). "Genes up-regulated in common in advanced human liver fibrosis and in Ezh1/2-KO mouse liver include biomarkers of liver disease (e.g. Golm1) and genes that play a fundamental role in liver fibrogenesis and HCC (e.g., Spp1/Osteopontin)." (PMID 32428001, 2020). "However, researchers found that colitis induced monocyte/macrophage infiltration in the gut and liver, promoting the expression of cholestasis-induced MoMF-Trem2 and Spp1, yet did not exacerbate liver fibrosis." (PMID 38276550, 2024). "Additionally, the expression of Fsap from iHEAs may enable decreases in HSC activation genes such as α-SMA, Lox, and Spp1 in the liver of DDC-induced cholestatic liver fibrosis mice, thereby ameliorating liver fibrosis." (PMID 35883684, 2022). "The expression of Fcgr2b and Spp1 was increased only in aggravated fatty liver, and the expression levels of Cxcl2 and Elane increased when liver fibrosis occurred which is not completely reversible, suggesting that these genes may play a key role in the prognosis of NAFLD." (PMID 36426356, 2022).
colon carcinoma (92 papers, 2006 to 2025). "SPP1+ TAMs are also implicated in T cell suppression, and play a role in immune evasion in the cancers such as colon cancer." (PMID 38347955, 2023). "SPP1 expression is upregulated in lung adenocarcinoma and colon cancer and its upregulation is associated with decreased patient survival and cancer metastasis." (PMID 37251946, 2023). "Spp1+ TAMs exhibited senescence-associated secretory phenotype, which were spatially located in closer proximity to adjacent senescent cancer cells in high-grade colon tumors." (PMID 40865052, 2025). "SPP1 (Secreted Phosphoprotein 1) encodes the osteopontin, which has been found to abnormally express in a variety of cancers, and induces drug resistance, progression, recurrence, and metastasis in breast, ovarian, and colon cancer." (PMID 37152062, 2023). "SPP1 is a secreted, integrin-binding phosphoprotein (osteopontin) which has been associated with tumour progression in multiple tumour types, including breast, hepatocellular, prostate, and colon carcinomas." (PMID 24865347, 2014). "Knocking out SPP1 in colon tumor cells increased the CTL lytic activity of T cells in vitro and inhibited tumor growth in vivo, whereas the protein level of OPN increased in the peripheral blood of tumor-bearing mice." (PMID 38919629, 2024). "Among these, the SPP1 signaling pathway, a characteristic gene of the Ma1 subgroup, is highly active in colon cancer, whereas the SELPLG and LIGHT signaling pathways are highly active in rectal cancer." (PMID 37675100, 2023). "Using human benign colon tissues and colon tumor tissues, we found that SPP1+ macrophages were particularly enriched in high-grade tumors." (PMID 37090726, 2023). "Similar to SPP1+ macrophages in colon cancer, SPP1+ TAMs in HPSCC display pro-angiogenic, pro-tumorigenic, and pro-metastatic properties." (PMID 37853464, 2023). "Eight significantly over‐expression genes in tumour tissues (BGN, THBS2, SPARC, CDH11, MFAP2, MMP11, SPP1 and THY1) were defined as significantly signature genes that implicated in colon cancer metastasis progress." (PMID 36377223, 2022). "In colon cancer patients, two main populations of TAMs with distinct functional features have been identified by transcriptomic analyses: Secreted phosphoprotein 1 (SPP1) positive TAMs and complement C1q C chain (C1QC) positive TAMs." (PMID 36189323, 2022). "Previous studies have reported that SPP1 overexpression promotes the proliferation and restrains the apoptosis of ovarian and colon cancer cells." (PMID 36266702, 2022). "Survival analysis showed that the differential expression of SPP1, CFRT, and KLF4 were associated with poor prognosis in colon cancer." (PMID 35733095, 2022). "Five genes (BGN, THBS2, SPARC, CDH11 and SPP1) were initially identified as potential biomarkers and therapeutic targets of colon cancer metastasis." (PMID 36377223, 2022). "Knocking out Spp1 in colon tumor cells increased tumor-specific CTL cytotoxicity in vitro and resulted in decreased tumor growth in vivo." (PMID 33670921, 2021). "High expression of SPP1 was reported to be involved in tumour invasion, progression, and metastasis in multiple cancers, including breast, ovarian, and colon cancer." (PMID 33287873, 2020). "In human colon cancer, SPP1 is a transcriptional target of aberrant Wnt signalling, and SPP1 expression alone predicts survival." (PMID 25884485, 2015). "Furthermore, SPP1+ macrophages were shown to accumulate preferentially in hypoxic and necrotic tumor regions, correlating with poor outcomes in colon cancer patients." (PMID 41176774, 2025). "Macrophage-positive SPP1-expressing colon cancer patients have shorter progression-free survival." (PMID 38886539, 2024). "Moreover, another in vivo study has demonstrated the mechanisms of the SPP1 – CD44 axis in colon cancer in a mouse model, that the osteopontin acts as an immune checkpoint to suppress T cell activation and promotes tumor immune evasion in colon carcinoma." (PMID 39691723, 2024).
colon carcinoma (continued). "SPP1 mRNA level had significant predictive value for survival in both rectal and colon cancers." (PMID 36895491, 2023). "Similarly, SPP1, a feature gene for the C3 subtype, has been reported to be positively correlated with colon cancer liver metastasis in SPP1+ macrophages and highly expressed in CMS4 (mesenchymal subtype)." (PMID 37267125, 2023). "In addition, SPP1+macrophages possessed anti-inflammatory phenotypes, which played a role in immune suppression and tumor evasion in colon cancer." (PMID 38347955, 2023). "Notably, SPP1+ TAMs were resistant to CSF1R blockade in a mouse model, and high infiltration of SPP1+ TAMs in colon cancer patients had a poor prognosis." (PMID 35898884, 2022). "Significantly, we found that the percentage of SPP1+ macrophages was highest in the deep GC layer, followed by the superficial GC layer, while it was absent in normal gastric tissues; these results are similar to a previous study on colon cancer." (PMID 36612160, 2022). "Expression of canonical Wnt target genes, such as the stemness marker Leucine-rich repeat-containing G-protein coupled receptor 5 (Lgr5) and osteopontin (Opn, Spp1) on mRNA level was significantly higher in SI and colon tumors in comparison to normal intestinal tissue." (PMID 31681563, 2019). "Using connectivity mapping, OPN and the top 15 OPN co‐regulated genes, we have identified 53 small molecules that could potentially reverse colon cancer OPN gene (SPP1) signature passing the perturbation stability test among 1432 candidate drugs." (PMID 29851214, 2018). "Osteopontin (OPN), also known as secreted phosphoprotein 1 (SPP1), binds to several integrin receptors including CD44v6, a splicing variant of CD44, which is a marker of colon cancer stem cells, and regulates cell motility, invasion, chemotaxis, and cell survival." (PMID 28505114, 2017). "In MC38 colon tumors, repeated anti-CD40 or radiotherapy created necrosis that split TAMs into peripheral Cxcl9+ and peri-necrotic Spp1+ subsets." (PMID 41176316, 2025). "The results unraveled that CCL5, THBS, SPP1, ICAM, and TNF signaling pathways were more abundant in colon cancer (red), whereas SELPLG, LIGHT, CSF, and BAFF signaling pathways were more abundant in rectal cancer (green)." (PMID 37675100, 2023). "In patients with colon cancer, OS (p=0,0108) and PFS (p=0,0139) rates were lower in cases with higher expression of SPP1 (>cut-off)." (PMID 36895491, 2023). "SPP1 mRNA expression was found to have a more significant predictive value for PFS in both rectal and colon cancers." (PMID 36895491, 2023). "Besides, the C1QC+ TAMs and SPP1+ TAMs could not be explained by the expression analyses based on genes associated with M1 and M2 TAMs in the colon cancer." (PMID 34295336, 2021). "The results also supported that SPP1, COL11A1, ADAM12, and INHBA expressions were significantly higher in colon cancer tissues compared to that of the normal tissues in accordance with our previous study." (PMID 30746900, 2019). "Interestingly, that stromal expression of SPARC and SPP1 was prognostic for the reduced RFS and PFS, respectively, only in rectal cancer patients, while S100A4 correlated with poor OS rates in CRC and colon cancer patients." (PMID 36895491, 2023). "Single-cell analyses of colon cancer revealed that TAMs could be divided into C1QC+ TAMs and SPP1+TAMs." (PMID 35558087, 2022). "We found that SPP1, VIP, COL11A1, CA2, ADAM12, INHBA could provide great significant prognostic value for colon cancer." (PMID 30746900, 2019). "At single-cell level, C1QC+ and SPP1+ TAMs gene signatures, but not M1 and M2 gene signatures, could clearly divided TAMs into two subclusters in a colon cancer data set and an advanced basal cell data set." (PMID 34295336, 2021).
colon carcinoma (continued). "First, we found that C1QC+ and SPP1+ TAMs gene signatures, but not M1 and M2 gene signatures, could clearly divided TAMs into two subsets in a colon cancer data set and an advanced basal cell carcinoma data set at single cell level." (PMID 34295336, 2021). "A significant overlap was detected with several relevant gene families, including colon cancer progression (e.g., FN1, IGBP3, PLAUR and TIMP1; P=0.00052), tumour cell apoptosis (e.g., BID, TNFRSF21, PHLDA1 and NOTCH1; P=1.46 × 10–6) and cell proliferation (e.g., CTGF, SPP1, FOLR1 and SPARC)." (PMID 21119668, 2010).
ovarian carcinoma (90 papers, 2004 to 2026). A malignant neoplasm originating from the surface ovarian epithelium. "In ovarian cancer, SPP1 expression is positively linked to the presence of CD4 + T cells, CD8 + T cells, macrophages, neutrophils, and dendritic cells." (PMID 41391064, 2025). "Elevated SPP1 expression is associated with poor prognosis in tumors such as esophageal, colorectal, lung, and ovarian cancers, as well as glioma." (PMID 41425545, 2025). "There was a significant association between SPP1 and DC markers in ovarian cancer, where SPP1 regulated DC infiltration." (PMID 38919629, 2024). "Previous studies have identified SPP1 as a biomarker for prognosis in ovarian cancer, which associated with enhanced immune cell infiltration." (PMID 39605915, 2024). "Next, we evaluated the associations between SPP1 expression and immune subtypes in ovarian cancer by TISIDB database." (PMID 36585688, 2022). "We further investigated the associations between SPP1 expression and molecular subtypes in ovarian cancer." (PMID 36585688, 2022). "Our findings in this report highlight the vital role of SPP1 in ovarian cancers and further offer a probable relationship and underlying mechanisms between SPP1 and tumor-immune interactions." (PMID 36585688, 2022). "We further observed that dendritic cell infiltration and SPP1 expression were significantly associated with the prognosis of ovarian cancer, although the prognostics value was completely different." (PMID 36585688, 2022). "We analyzed the association of SPP1 with tumor infiltration immune cells in the ovarian cancer microenvironments via TIMER and TISIDB." (PMID 36585688, 2022). "SPP1 is reportedly involved in promoting ovarian cancer cell survival and progression and could be a good diagnostic marker for ovarian carcinoma." (PMID 35578123, 2022). "Current insights into SPP1’s role in ovarian cancer highlight its impact on tumor cells and the TME." (PMID 41391064, 2025). "Researchers discovered that SPP1 levels were significantly higher in several tumors, including ovarian cancer, indicating its potential role in tumor progression." (PMID 41391064, 2025). "Initial studies on SPP1 in ovarian cancer involved analyzing gene expression data across various cancers." (PMID 41391064, 2025). "Preclinical studies in ovarian cancer models showed that anti-SPP1 antibody treatment reduced tumor volume, accompanied by improved immune cell function." (PMID 41425545, 2025). "Effects on Tumor Cells: In epithelial ovarian cancer, SPP1 expression is elevated, enhancing cancer cell migration, invasion, and growth." (PMID 41391064, 2025). "One study confirmed high SPP1 expression in ovarian cancer cells through immunohistochemistry and examined its link to tumor-infiltrating immune cells." (PMID 41391064, 2025). "The SPP1 gene was expressed at a significantly higher level in ovarian cancer cells A2780 than in normal ovarian cells IOSE80, which also demonstrated the accuracy of our experiment." (PMID 37143732, 2023). "We found that the loss of CTGF in epithelial ovarian cancer cells is associated with modifications on the expression of several genes associated with the ECM, including LAMC2 SPP1, SV2A, RELN, COL6A3, and COL4A6." (PMID 37835529, 2023). "All the results suggested that SPP1 mRNA was upregulated in most carcinoma including ovarian cancer." (PMID 36585688, 2022). "We next investigated the correlation between SPP1 expression and clinical outcomes of ovarian cancer." (PMID 36585688, 2022). "Secreted phosphoprotein 1 (Spp1) is expressed in ovarian granulosa cells and promotes ovarian cancer progression; however, its role in ovarian GCT development is unclear." (PMID 35565312, 2022). "We found that SPP1 expression was correlated with C1, C2, C3 and C4 in ovarian cancer (p = 3.37e-03)." (PMID 36585688, 2022).